MAGEA1 (MAGE family member A1)
Description:
May be involved in transcriptional regulation through interaction with SNW1 and recruiting histone deactelyase HDAC1. May inhibit notch intracellular domain (NICD) transactivation. May play a role in embryonal development and tumor transformation or aspects of tumor progression. Antigen recognized on a melanoma by autologous cytolytic T-lymphocytes.
Synonyms: CT1.1; MAGE1; MGC9326
Tractability: Antibody: its Gene Ontology location is reachable by antibodies, with high confidence. PROTAC: ubiquitination databases record sites on it.
Gene: Protein-coding gene on chromosome X (153,179,284 to 153,183,880, forward strand). Ensembl gene ENSG00000198681.
Subcellular location: Cytoplasm; Nucleus
Subcellular location (Human Protein Atlas): Cytosol
Gene Ontology:
Molecular function: histone deacetylase binding; protein binding
Biological process: negative regulation of Notch signaling pathway; negative regulation of transcription by RNA polymerase II
Cellular component: cytoplasm; cytosol; nucleus; plasma membrane
Homologues: Orthologues: chimpanzee MAGEA1 (98% identical), zebrafish ndnl2 (23% identical), Drosophila melanogaster MAGE (17% identical). Paralogues in human: MAGEA4 (77% identical), MAGEA8 (69% identical), MAGEA6 (69% identical), MAGEA12 (68% identical), MAGEA2 (68% identical), MAGEA2B (68% identical), MAGEA3 (68% identical), MAGEA9 (62% identical), MAGEA9B (62% identical), MAGEA11 (61% identical), MAGEA10 (56% identical), MAGEB16 (47% identical), and 25 more.
Diseases named in the same sentence as MAGEA1 in open-access papers:
MAGEA1 is named in the same sentence as 69 diseases in open-access papers, as found by Europe PMC text mining. Sharing a sentence is not in itself a finding about the gene and the disease. The quoted sentences say what the papers report.
melanoma (78 papers, 2004 to 2026). A malignant, usually aggressive tumor composed of atypical, neoplastic melanocytes. "Together, our results suggested that DNA demethylation and activation of MAGEA1 in melanoma cells is associated with loss of H3K9me2, and gains of H3ac and H3K4me2 within the 5′-region of the gene." (PMID 23472218, 2013). "The first CT gene discovered was MAGEA1 that encodes for an antigen of human melanoma." (PMID 23691492, 2013). "In MAGEA1 Glu217 (corresponding to Phe235 in yeast Nse3) was mutated to Lys in a melanoma sample." (PMID 21364888, 2011). "Several ongoing clinical trials for cancer treatment, including those targeting melanoma and neuroblastoma, utilize MAGEA1 or MAGEA3 as targets." (PMID 41345672, 2025). "The knockdown of YBX1 in melanoma cells led to a reduction in MAGEA1 mRNA levels, while overexpression of YBX1 significantly increased MAGEA1 expression." (PMID 39716999, 2025). "De novo expression of MAGEA1 in melanoma cells was detectable up to 2–5 months after the end of DAC treatment." (PMID 40791813, 2025). "The result of TCGA analysis indicated the expression of MAGEA1 was up‐regulated in melanoma and correlated with tumor metastasis." (PMID 39716999, 2025). "Other peptides of interest included peptides previously reported as immunogenic and derived from PReferentially expressed Antigen in MElanoma (PRAME), Melanoma associated antigen A1 (MAGEA1), and Ephrin receptors proteins." (PMID 37637064, 2023). "Among them, MAGEA1, A2, and A3 were originally well-described antigens in melanoma and cancer originating from the testis." (PMID 35205608, 2022). "In this study, the uMAGEA assay increased melanoma detection by 13% compared with the MAGEA1 assay alone, and by 17% compared with the MAGEA3 assay alone in melanoma tumors." (PMID 35205608, 2022). "In contrast, the top SFPQ-enriched mRNA transcripts in melanoma cells were generally associated with disease progression, such as AMIGO2, MAGEA3, MAGEA1, and the transcription factor, SOX10." (PMID 34218270, 2021). "The first member of the human MAGE family, MAGE-1, was identified from a human melanoma cell line, which was later renamed MAGEA1 upon the discovery of additional gene family members." (PMID 34788311, 2021). "Shortly afterward, the first human tumor antigen gene was identified in melanoma, namely, MAGEA1 (melanoma antigen family A, 1) and was found to be expressed in various types of tumors." (PMID 29276510, 2017). "Such association was confirmed in our present study, as we found that MAGEA1 demethylation and activation in melanoma cells correlated with losses of H3K9me2, and gains in H3ac and H3K4me2." (PMID 23472218, 2013). "The expression of P21 was negatively correlated with MAGEA1 and regulated by MAGEA1 in melanoma." (PMID 39716999, 2025). "Indeed, the identification of MAGEA1 in ex vivo assays using cytotoxic T cells from melanoma patients was the first evidence that reactive tumor antigens do exist." (PMID 37341056, 2023). "MAGEA1, an antigen present in melanoma, is correlated with a poor prognosis in NSCLC." (PMID 37081975, 2023). "In addition, it was demonstrated that the downregulation of DNMT1 activated a methylated MAGEA1 transgene in melanoma cells, strengthening the theory that DNA methylation is the primary mode of expression regulation for CTAs." (PMID 36980267, 2023). "This is notable due to the frequent expression of CT genes in melanomas; e.g., MAGEA1." (PMID 20305816, 2010). "Importantly, MZ2-MEL.TrHM cells were derived from a MAGEA1-expressing melanoma cell line." (PMID 23472218, 2013).
melanoma (continued). "We continued to assess the effect of DAC treatment on the expression of MAGEA1, MAGEA3/MAGEA6, and MAGEA9 in a broad panel consisting of 37 cell lines originating from female reproductive organ tumors, melanoma, hematopoietic, or other cancers." (PMID 40791813, 2025). "Levels of expression of GAGE, NY-ESO1, MAGEA1, PASD1, PRAME in melanoma cell lines were significantly higher than in STBS group (adj." (PMID 32042403, 2020). "We undertook a mutational analysis of coding regions of four CT-X MAGE genes, MAGEA1, MAGEA4, MAGEC1, MAGEC2 and the ubiquitously expressed MAGEE1 in human melanoma samples." (PMID 20862285, 2010). "Among these, T cells recognize known melanoma antigens such as MART1, PMEL, and MAGEA1, as well as unknown sequences that might be neoantigens." (PMID 39312285, 2024). "The results confirmed that a number of TCRs matched known MART1-reactive clonotypes but also revealed matching TCRs that might recognize other melanoma antigens, such as PMEL and MAGEA1." (PMID 39312285, 2024). "For example, MAGEA1 is upregulated in lung cancer, melanoma, and gastric cancer; MAGEA3 is upregulated in breast and lung cancer; MAGEA4 is upregulated in melanoma; MAGEA5 is upregulated in head and neck cancer; and MAGEA9 is upregulated in liver and colon cancer." (PMID 34202157, 2021). "This was assessed by testing the effect of trichostatin A (TSA), a histone deacetylase inhibitor, in non-expressing melanoma cells and in a cell clone harboring a methylated MAGEA1/hph construct, which allows selection (hygromycin resistance) of cells where activation of the transgene occurred." (PMID 23472218, 2013). "However, expression of TDRD9 is not correlated with that of MAGEA1, MAGEA2, MAGEA3, or MAGEA4, which are CTA genes often expressed in lung cancer and melanomas." (PMID 29515758, 2018). "Experiments were performed on immortalized human foreskin fibroblasts (HFF2-hTERT) and two melanoma cell lines that do not express MAGEA1 (SK-MEL-23 and EB16-MEL), as well as on three melanoma cell lines that do express MAGEA1 (MZ2-MEL3.1, BB74-MEL and Mi13443-MEL)." (PMID 23472218, 2013).
lung carcinoma (17 papers, 2006 to 2025). "Melanoma-associated antigen 1 (MAGEA1) is a member of the melanoma-associated antigens family A (MAGE-A) and is closely related to the prognoses of various malignant tumors, such as esophageal squamous cell carcinoma, lung cancer, gastric cancer, liver cancer, and breast cancer." (PMID 33680915, 2020).
ovarian carcinoma (17 papers, 2012 to 2025). A malignant neoplasm originating from the surface ovarian epithelium. "MAGEA8 is a CT antigen whose expression in normal adult tissues is restricted to the testis and placenta; family members MAGEA3, MAGEA1 were also scored by immunotherapy experts (ranks 8 and 44 out of 75) and have been shown to be expressed in ovarian cancers." (PMID 26622942, 2015). "Moreover, forced expression of MAGEA1 is known to increase the drug sensitivity of cisplatin‐resistant ovarian cancer cells due to induced epigenetic changes." (PMID 38351531, 2024). "Also, Melanoma-associated antigen A1 (MAGEA1) was shown to suppress cell proliferation and migration probably through FBW7-mediated NICD1 degradation in ovarian cancer." (PMID 33658012, 2021).
breast carcinoma (16 papers, 2006 to 2026). "Cancer-associated hypomethylation of TFF1 and MAGEA1 was also observed by Illumina HumanMethylation450 analysis of DNA methylation in the TCGA database for breast cancer and paired normal samples." (PMID 26510686, 2015). "The last gene region we examined was MAGEA1, which encodes a cancer-testis antigen that is not expressed in normal somatic tissues but is sometimes expressed in breast cancer." (PMID 26510686, 2015). "MAGEA1/3/12/13, MMP11/13, PRAC2, CSAG1, COL10/11A1 genes are overexpressed in breast cancer samples from patients with PP." (PMID 36675137, 2023). "Cancer-testis antigen genes are often hypomethylated in various kinds of cancer, although the methylation status of MAGEA1 in breast cancer was not known." (PMID 26510686, 2015). "A total of 137 breast cancer tissue specimens including 51 triple-negative breast cancer (TNBC) were assessed for MAGE-A4, MAGEA1, NY-ESO-1, KK-LC-1 and PRAME expression by immunohistochemistry." (PMID 37610673, 2023). "Of 16 CTAGs examined in the first panel of 42 breast cancer samples, seven antigens were found not to be expressed in any of the specimens: SSX2, SSX4, CTAG2, CAGE1, MAGEA1, MAGEA4 and MAGEA11." (PMID 17650306, 2007).
multiple myeloma (5 papers, 2013 to 2023). "This analysis revealed significant down-regulation by CYCLON knockdown of a proliferation gene expression signature that includes cancer testis antigens (e.g. MAGEA1, MAGEA3, MAGEA6, GAGE1), and that characterizes an aggressive subtype of multiple myeloma." (PMID 23828858, 2013).
astrocytoma (4 papers, 2004 to 2013). "However, the MAGEA1 gene that was inactivated and hypermethylated in non-astrocytoma tissues, was partially demethylated in 24.5% of the astrocytoma tissues (co-existence of the hypermethylated and demethylated alleles)." (PMID 15367334, 2004). "Demethylation mediated inducible expression of the CDH13, MAGEA1, MGMT, p73 and RASSF1A genes was established in an astrocytoma cell line (U251), demonstrating that expression of these genes is likely regulated by DNA methylation." (PMID 15367334, 2004).
bladder cancer (4 papers, 2006 to 2024). "It was found that frequencies of genomic alterations among MAGEA family members in bladder cancer were MAGEA1 1.8%, MAGEA2 1.6%, MAGEA3 1.9%, MAGEA4 1.6%, MAGEA6 2.6%, MAGEA8 1.7%, MAGEA10 2%, MAGEA11, 2.1%, and MAGEA12 2.4%." (PMID 38254738, 2024). "Other MAGEA family members, including MAGEA1 and MAGEA8, exhibited lower expression in bladder cancer compared to normal bladder specimens." (PMID 38254738, 2024).
colon carcinoma (4 papers, 2020 to 2024). "For example, in prostate, ovarian, and colon cancer cells, the MAGEA1 and MAGEA11 promoters are hypomethylated, and their expression is increased." (PMID 34202157, 2021). "By studying colon cancer pathologic specimens, we confirmed that DYDC2, MS4A15, MAGEA1, WNT7A, APOD, and SERPINE1 were highly expressed in colon cancer tissues." (PMID 33680915, 2020).
hepatocellular carcinoma (3 papers, 2004 to 2018). A malignant tumor that arises from hepatocytes. "Our qRT-PCR analyses revealed that the mRNA expression levels of MAGEA-3, MAGEA-1, p16, and p15 were significantly increased in the hepatocellular carcinoma HepG2 cell lines after treatment with 10 nM DAC for 72 h and that the RASSF1A and BRCA1 levels were unchanged." (PMID 24963497, 2014). "A prominent example is the gene encoding the melanoma antigen, MAGEA1 that was hypermethylated and transcriptionally silenced in the normal liver tissues, and demethylated prevalently in the hepatocellular carcinoma tissues, correlating well with the elevated level of its expression in HCC." (PMID 15367334, 2004). "In line with this argument, studies have shown that hypomethylation in the promoter region of oncogenes, RRAS, S100P, and melanoma antigen family A1 (MAGEA1) activates their gene expression in gastric, pancreatic, and hepatocellular carcinoma, respectively." (PMID 30402498, 2018).
osteosarcoma (3 papers, 2020 to 2025). A usually aggressive malignant bone-forming mesenchymal neoplasm, predominantly affecting adolescents and young adults. "Osteosarcoma was characterized by the presence of GAGE (40% 2/5), MAGEA1 (60% 3/5), PRAME (40% 2/5), NY-ESO1 (40% 2/5), PASD1 (60% 3/5), SLLP1 (60% 3/5), SSX1 (80% 4/5)." (PMID 32042403, 2020).
brain tumor (2 papers, 2013 to 2026). "Cell lines showed variable induction of NY-ESO-1 and MAGEA1, confirming that DAC treatment can induce expression of these neoantigens across a variety of brain tumor cell types." (PMID 41541220, 2026).
Obesity (1 paper, 2016). Accumulation of substantial excess body fat. "Moreover, two tested CTAs were significantly downregulated in smoking patients (MAGEA1, AE; FBXO39, AE and RE) and one CTA (LDHC) seemed to be upregulated (AE) in patients with obesity." (PMID 27635108, 2016).
ovarian tumor (1 paper, 2023). "For ovarian tumor samples, we detected six hub genes: GAGE2A, GAGE1, MAGEA9, CTAG1A, CTAG1B, and MAGEA1." (PMID 37835834, 2023).
round cell liposarcoma (1 paper, 2022). A poorly differentiated liposarcoma, characterized by the presence of solid sheets of primitive round mesenchymal cells and the absence of myxoid stroma. "CTAG2 (encodes cancer-testis antigen 2) and MAGEA1 were shown to be expressed consistently in myeloid and round-cell liposarcomas; hence, these genes are used as immunotherapy targets in the treatment of these cancers." (PMID 35565356, 2022).
sarcomatoid mesothelioma (1 paper, 2024). A diffuse malignant mesothelioma arising from the pleura and less often the peritoneum. "Conversely, several genes reported to be expressed in sarcomatoid mesothelioma were preferentially expressed in cluster 1: members of the MAGE family MAGEA1, MAGEA3, MAGEB2 and MAGEA6." (PMID 38212075, 2024).
synovial sarcoma (1 paper, 2020). "The activity of MAGEA1 (25% 1/4), NYESO1 (50% 2/4), and PRAME (75% 3/4) genes were also found in the cells of four samples of synovial sarcomas." (PMID 32042403, 2020).